METTL3 (methyltransferase 3, N6-adenosine-methyltransferase complex catalytic subunit)
Diseases named in the same sentence as METTL3 in open-access papers (continued):
Sharing a sentence is not in itself a finding about the gene and the disease.
leukemia (continued). "A recent study showed that METTL3 depletion blocked leukemia cell growth, induced differentiation and apoptosis, and delayed leukemia development in immunodeficient recipient mice." (PMID 34001273, 2021). "Overexpression of METTL3 inhibits leukemia cell differentiation and increases cell growth; conversely, deletion of METTL3 in human myeloid leukemia cells can induce cell differentiation and promote apoptosis, and delay in vivo leukemia development." (PMID 34485297, 2021). "There are few pieces of researches focused on mutations in m6A-related genes in prostate cancer, but in AML, mutations in m6A writers such as METTL3, METTL14 and WTAP can enhance progression of leukemia, conferring unfavorable survival outcomes." (PMID 32710725, 2020). "In immunodeficient mice, downregulation of METTL3 led to cell cycle arrest, leukemia cell differentiation, and the inability to establish leukemia." (PMID 32398132, 2020). "Deletion of METTL3 in a human myeloid leukemia cell line was shown to induce the differentiation and apoptosis of cells in recipient mice and delay the occurrence of leukemia." (PMID 32398132, 2020). "Collectively, research in leukemia suggests that METTL3 is upregulated and significantly related to tumor cell differentiation, tumor formation, the cell cycle, and proliferation." (PMID 31921660, 2019). "According to the recent research conducted by Ly P Vu and colleagues, leukemia cells show an elevated abundance of METTL3 as compared to normal hematopoietic cells." (PMID 29587823, 2018). "METTL3 depletion in normal human hematopoietic stem/progenitor cells (HSPCs) and leukemia cells leads to a decline in RNA m6A levels, to promotion of differentiation, and to reduction of proliferation in HSPCs and myeloid leukemia cells." (PMID 30405719, 2018). "More interestingly, METTL3 depletion delays leukemia progression in in vivo mice, altogether suggesting the potential of METTL3 as a therapeutic target for AML." (PMID 30405719, 2018). "Depletion of METTL3 in human myeloid leukemia cell lines induces cell differentiation and apoptosis and delays leukemia progression in recipient mice in vivo." (PMID 29587823, 2018). "More importantly, STM2457 attenuated the growth of leukemia cells and promoted their differentiation as well as apoptosis in vitro, and the METTL3 inhibitor prolonged the survival of leukemia mice models by impairing leukemia cell engraftment and suppressing leukemic stem cell subpopulations." (PMID 40612868, 2025). "Finally, we found a novel METTL3 inhibitor, a natural product called isoliquiritigenin, with potential anti-leukemia activity." (PMID 40169588, 2025). "Additionally, we identified the natural product isoliquiritigenin as a novel drug that potentially targets METTL3, which exhibits promising anti-leukemia properties." (PMID 40169588, 2025). "For instance, STM2457, a recently unearthed inhibitor of METTL3, has demonstrated significant antineoplastic efficacy against leukemia in both laboratory and animal models, thereby affirming the potential of METTL3 as a viable target in anticancer therapeutics." (PMID 38577917, 2024). "Two other METTL3 inhibitors (Compound 1 and Compound 2), which were verified in a structure-guided medicinal chemistry platform, can reduce the abundance of METTL3-methylated mRNAs and suppressing the proliferation of leukemia cells both in vivo and in vitro." (PMID 36810108, 2023). "For instance, STM2457 targets METTL3 and METTLl4, the key components of m6A methyltransferase, and were reported to significantly inhibit the proliferation, induce the differentiation, and increase the apoptosis of leukemia cells." (PMID 37692484, 2023). "METTL3 is able to mediate myeloid differentiation of leukemia cells." (PMID 35761379, 2022).
leukemia (continued). "Methyltransferase 3(METTL3) increased the translation of downstream leukemia-related genes, such as MYC, BCL2, and PTEN mRNA, in an m6A-dependent manner, and depletion of METTL3 blocked proliferation, induced differentiation, and apoptosis in immunodeficient recipient mice." (PMID 35865470, 2022). "In addition, they found that METTL3 disruption promotes the differentiation and apoptosis of AML cells both in vitro (MOLM-13 cells) and in vivo, which indicated that METTL3 affects the undifferentiated state and growth of leukemia cell lines." (PMID 35574332, 2022). "The therapeutic potential of METTL3 as an anti-leukemia target has elicited considerable interest, for exploring its inhibitors to intervene the proliferation, differentiation, and apoptosis of leukemia cells." (PMID 35999621, 2022). "METTL3 can mediate the myeloid differentiation of leukemia cells." (PMID 35761379, 2022). "Similarly, downregulation of METTL3 resulted in differentiation of leukemic cells and failure to establish leukemia in mice." (PMID 34805173, 2021). "Furthermore, it was also reported that the adoptive transfer of Mettl3-deficient human AML cell line (MOLM-13) into immunodeficient (recipient) mice induces cell-differentiation and apoptosis but remarkably delayed leukaemia progression." (PMID 34207299, 2021). "For example, METTL3 could induce m6A modification in coding region of mRNA transcription related to the cell cycle, which is essential for the differentiation of leukemia cells and ultimately promotes the translation of a variety of oncogenic mRNAs." (PMID 34123827, 2021). "Consequently, METTL3 inhibits hematopoietic stem/progenitor cell differentiation and increases leukemia cell growth, and METTL3 depletion induces cell-cycle arrest, cell differentiation, and apoptosis and delays leukemia progression in mice." (PMID 32316617, 2020). "Moreover, another study revealed that knockdown of METTL3 results in differentiation of leukemic cells, failure to establish leukemia in immunodeficient mice, coupled with cell cycle arrest." (PMID 31921660, 2019). "To investigate whether m6A play a role in the emergence and development of leukemia, we performed real‐time fluorescent quantitative PCR to detect the mRNA expression level of METTL3 and MTEEL14 in E/R‐positive ALL." (PMID 31429529, 2019). "Another study confirmed the important roles of METTL3 in leukemia progression." (PMID 29439529, 2018). "Additionally, depletion of METTL3 in human myeloid leukemia cell lines induces cell differentiation and apoptosis, while suppressing leukemia progression in recipient mice in vivo." (PMID 29439529, 2018). "Furthermore, depletion of METTL3 in human myeloid leukemia cell lines facilitates differentiation and apoptosis and delays leukemia development in recipient mice in vivo." (PMID 30149601, 2018). "Furthermore, our results showed that METTL3-CD also lost its superiority in promoting cellular growth and clonogenic ability of human leukemia cells caused by METTL3 in the presence or absence of IDA." (PMID 36266324, 2022). "Given the implication of METTL3 in the development and progression of numerous cancer types, there has been considerable interest in small molecule METTL3 inhibitors, that have recently demonstrated preclinical proof of concept evidence for the treatment of leukaemia." (PMID 36733939, 2022). "Because METTL3 plays a critical role in catalytic activity, many studies regarding its biological function in cancers have been widely reported, including lymphoma, leukemia, breast cancer progression, liver cancer, glioblastoma, bladder cancer, gastric cancer, and lung cancer." (PMID 35574332, 2022). "Highly selective inhibition of the METTL3/METTL14 complex and demonstration of anti-leukemia activity in AML cell lines including MOLM-13, MOLM-14, HL60, etc." (PMID 41157107, 2025). "Inhibiting METTL3 in AML cells not only induces differentiation but also increases apoptosis and slows the progression of leukemia." (PMID 39295872, 2024).
leukemia (continued). "These inhibitors, such as Eltrombopag and CDIBA-4, bind directly the METTL3–METTL14 heterodimer, impacting its catalytic activity, which correlates with severely impaired proliferation in MOLM-13 cells and other leukemia cell lines." (PMID 38444581, 2024). "Elevated expression of METTL3 in AML has been shown to promote proliferation and chemoresistance, and decrease apoptosis in leukemia cells." (PMID 37280654, 2023). "Of the proteins involved in RNA modification, the m6A METTL3-METTL14 writer complex, m6A reader YTHDF2, and m6A eraser FTO and ALKBH5 have all been shown to play a role in MLL-r leukemia." (PMID 36307883, 2022). "Small-molecule inhibitors of METTL3, FTO, ALKBH5 have recently been identified and have exhibited considerable anti-leukemia effects both in vitro and in mouse models." (PMID 35999621, 2022). "Supporting this, shRNA-mediated knockdown of METTL3 in the MLL-AF9 expressing human AML cell line, MOLM-13, led to apoptosis, differentiation, and a delay in leukemia development in recipient mice." (PMID 36307883, 2022). "The consumption of METTL3 leads to an increase in the level of phosphorylated AKT, induces apoptosis, and delays the progression of mouse leukemia." (PMID 34858499, 2021). "METTL3/14 was expressed more abundantly in AML cells than in healthy HSCs/HPCs, which contributed to the leukemia progression in vivo." (PMID 34805173, 2021). "For instance, increased expression of several m6A modifiers such as METTL3, FTO, and ALKBH5 have been observed in leukemia cells (discussed in the following)." (PMID 34485297, 2021). "More importantly, the METTL3/METTL14 methylation complex was found to promote the development of AML and maintain leukaemia-initiating cells in transplantation mouse models." (PMID 30096915, 2018). "For example, m6A mediated by METTL3 and METTL14 methyltransferase complex is an abundant RNA modification on mammalian mRNA, which plays important roles in hematopoietic development and the maintenance of hematopoietic and leukemia stem cells." (PMID 40382345, 2025). "STM2457, the first METTL3 inhibitor, was validated to reduce the m6A deposit on several oncogenes (such as HOXA10 and MYC), induce cell differentiation, and effectively inhibit the growth of leukemia cells." (PMID 37028765, 2023). "Next, the expression of METTL3 and METTL14 in leukemia cell lines was examined." (PMID 35154467, 2022). "METTL3, the main m6A methyltransferase, inhibits cell differentiation and apoptosis and promotes cell proliferation by increasing the translation of c-myc, bcl-2 and PTEN in leukemia." (PMID 33658391, 2021). "In this case, depletion of METTL3 increased the phosphorylation of protein kinase B (AKT) and induced the differentiation and apoptosis of the leukemic cells, eliciting a delay in the progression of leukemia." (PMID 33061938, 2020). "Interestingly, a genome-wide CRISPR/Cas9 screening performed in mouse primary leukemia cells expressing both FLT3-ITD and MLL-AF9 fusion genes identified besides METTL3 and METTL14 also METTL16 as critical gene for AML survival." (PMID 31024852, 2019). "So we speculated that the downexpression of METTL3 and METTL14 in E/R‐positive ALL may affect the m6A modification of some genes in leukemic cells, and then promote the development of leukemia." (PMID 31429529, 2019).
leukemia (continued). "However, in transplantation experiments, mouse HSCs deleted for METTL3 or METTL14 showed reduced repopulation ability and the deletion of METTL14 from primary leukaemia blasts significantly delayed leukaemia onset in recipient mice." (PMID 30096915, 2018). "METTL3 has been reported to inhibit myeloid differentiation of normal hematopoietic and leukemia cells." (PMID 30149601, 2018). "Especially, METTL3 and METTL14 are also involved in various aspects of the occurrence and development of AML dependent or independent on their m6A methyltransferase activity, including maintenance of the leukemic state, therapeutic resistance, and leukemia cell survival and differentiation." (PMID 40382345, 2025). "METTL3 not only influences normal and symmetric HSPC/HSC differentiation, HSPC self-renewal, and colony formation ability in normal hematopoiesis but also affects leukemia cell differentiation, proliferation, apoptosis, chemoresistance, and a higher risk of specific ALL or lymphoma." (PMID 35574332, 2022). "Importantly, upregulation of WTAP is not enough to promote the proliferation of leukemia cells when the function of METTL3 is absent, indicating that the oncogenic role of WTAP depends on METTL3 and RNA m6A." (PMID 34485297, 2021). "Thus we speculate that the downexpression of METTL3 and METTL14 contributes to not only the development of leukemia but also to relapse." (PMID 31429529, 2019). "Further experiments revealed that WTAP could not execute its oncogenic role without METTL3, as WTAP failed to increase the proliferation level of leukemia cells with depressed METTL3." (PMID 35999621, 2022).
non-small cell lung carcinoma (87 papers, 2019 to 2026). A group of at least three distinct histological types of lung cancer, including non-small cell squamous cell carcinoma, adenocarcinoma, and large cell carcinoma. "Subsequent SUMOylation of METTL3 promotes colony formation and tumor growth of human non-small cell lung cancer (NSCLC) H1299 cells, which is caused by downstream gene dysregulation." (PMID 40495163, 2025). "Moreover, METTL3 and its associated m6A modifications were identified at higher levels in non-small cell lung cancer (NSCLC) cells than in adjacent normal tissues." (PMID 39972266, 2025). "In the tumor tissues of patients with primary non-small cell lung cancer, the positive expression rate of METTL3 is higher than that of normal tissues around the cancer, and the level of METTL3 is associated with the patient’s tumor size, depth of invasion, and lymph node metastasis." (PMID 33741902, 2021). "On the contrary, β-elemene induced METTL3 to positively regulate autophagy in non-small cell lung cancer resistant to Gefitinib." (PMID 39893158, 2025). "In non-small cell lung cancer, upregulation of METTL3 significantly accelerates the activates of the NF-κB signaling pathway, inducing drug resistance and metastasis of cancer cells." (PMID 39794323, 2025). "METTL3 regulates ferroptosis of non-small cell lung carcinoma through the expression of FSP1 in an m6A manner." (PMID 40175350, 2025). "Specifically, METTL3 modifies ncRNAs via m6A modification, thereby regulating RNA Pol II transcription and promoting non-small cell lung cancer." (PMID 41390674, 2025). "For example, METTL3 elevation promotes the progression of non-small cell lung cancer (NSCLC), but METTL3 also inhibits tumorigenesis in NSCLC." (PMID 38166703, 2024). "For instance, in non-small cell lung cancer, METTL3 positively regulates autophagy by increasing the expression of ATG5 and ATG7." (PMID 38576024, 2024). "For example, in non-small cell lung cancer, METTL3-mediated m6A methylation increased the stability of YAP mRNA by regulating Malat1-miR-1914-3p-Yap axis-induced chemotherapy resistance." (PMID 36932427, 2023). "In non-small-cell lung cancer, METTL3 can enhance the stability of long non-coding RNA DLGAP1-AS2 (DLGAP1 antisense RNA2) through its m6A reader function." (PMID 38202722, 2023). "METTL3, YTHDF3, and YTHDF1 promoted yes-associated protein (YAP) translation by inducing the m6A modification of YAP in non-small cell lung cancer cells (NSCLCs)." (PMID 36835633, 2023). "In non-small-cell lung cancer, METTL3-induced m6A modifications have been reported to enhance the stability and increase the expression of ABHD11-AS1 transcripts." (PMID 36982798, 2023). "In non-small cell lung cancer, METTL3 enhances lncRNA DLGAP1-AS2 stability via m6A modification and interacts with YTHDF1 to improve MYC RNA stability." (PMID 37996892, 2023). "In non-small cell lung cancer, METTL3 downregulates DAPK2 expression, leading to enhanced tumor migration in vitro and in vivo following the activation of the NF-KB signaling pathway." (PMID 37996892, 2023). "miR-33a is capable of reducing the METTL3 expression at both mRNA and protein levels, thus affecting proliferation, survival and invasion of non-small cell lung cancer." (PMID 36614216, 2023). "A pathway involving miR-600 and METTL3 is involved in the progression of non-small cell lung cancer (NSCLC), wherein miR-600 inhibits the expression of METTL3, thereby counteracting its positive effect on NSCLC progression." (PMID 37915034, 2023). "In non-small cell lung cancer, METTL3 induces m6A methylation of LncRNA ABHD11-AS1, enhances the stability of ABHD11-AS1 transcript to increase its expression, and promotes the proliferation of tumor cells and Warburg effect." (PMID 35022030, 2022). "METTL3 increases miR-1246 levels through m6A modification, thereby promoting non-small-cell lung cancer progression." (PMID 35012593, 2022).